SPINK8 (serine peptidase inhibitor Kazal type 8 (putative))
Description:
Probable serine protease inhibitor.
Tractability: Antibody: UniProt places it where antibodies can reach, with high confidence; UniProt predicts a signal peptide or a membrane-spanning region; its Gene Ontology location is reachable by antibodies, with medium confidence.
Gene: Protein-coding gene on chromosome 3 (48,306,842 to 48,333,661, reverse strand). Ensembl gene ENSG00000229453.
Subcellular location: Secreted
Gene Ontology:
Cellular component: extracellular region
Genetic constraint (gnomAD): Loss-of-function variants: 13 observed, 14.28 expected, observed/expected ratio (o/e) 0.91, 90% interval 0.59 to 1.44. The upper end of that interval is the gene's LOEUF score, 1.44, which puts it in group 5 of 6, group 1 being the genes least tolerant of losing a copy. Missense variants: 103 observed, 106.83 expected, observed/expected ratio (o/e) 0.96, 90% interval 0.82 to 1.14. Synonymous variants: 32 observed, 32.88 expected, observed/expected ratio (o/e) 0.97, 90% interval 0.73 to 1.31.
Homologues: Orthologues: chimpanzee SPINK8 (99% identical), macaque SPINK8 (92% identical), dog SPINK8 (66% identical), pig SPINK8 (58% identical), rat Spink8 (57% identical), mouse Spink8 (56% identical). Paralogues in human: SPINK2 (28% identical), SPINK7 (24% identical), SPINK14 (23% identical), SPINK9 (22% identical), SPINK13 (18% identical).
Diseases named in the same sentence as SPINK8 in open-access papers:
SPINK8 is named in the same sentence as 5 diseases in open-access papers, as found by Europe PMC text mining. Sharing a sentence is not in itself a finding about the gene and the disease. The quoted sentences say what the papers report.
breast carcinoma (2 papers, 2022 to 2023). "This study first identified SPINK8 as a biomarker for poor prognosis in breast cancer, and the role of SPINK8 should be fully elucidated." (PMID 36243728, 2022). "An AA metabolic signature (SPINK8, KLRB1, APOD and PIGR) was constructed for breast cancer prognosis." (PMID 36243728, 2022).
tumour (3 papers, 2020 to 2022). "All five genes in the module (AL121899.1, GFOD2, SPINK8, C2orf54 and CST6) were down‐regulated and lost positive correlations with their neighbours in tumour samples." (PMID 32164040, 2020). "OLFM4, SPINK8, CRYAB, KCNMA1, TFAP2B, and TFF1 were significantly upregulated during tumor progression in P8‐2 CTCs." (PMID 33377642, 2020).
SPINK8 also shares sentences with these, for which no sentence is quoted: cancer (1 paper); diabetes (1); Hyperglycemia (1).